CD4 (CD4 molecule)
Diseases named in the same sentence as CD4 in open-access papers (continued):
Sharing a sentence is not in itself a finding about the gene and the disease.
substance abuse (24 papers, 2008 to 2023). The use of a drug for a reason other than which it was intended or in a manner or in quantities other than directed. "Those with low CD4 cell counts, who are underweight, or currently having substance abuse should be carefully monitored." (PMID 35387594, 2022). "Individual factors influencing the practice of engagement behaviour include information, motivation and behavioural skills, self-efficacy, acceptance of diagnosis, demographics, clinical state (such as CD4 count) and comorbidities (including mental health and substance abuse amongst others)." (PMID 37143067, 2023). "As expected, virtually all providers would prescribe ART to a typical patient with no substance abuse history and a CD4+ count of 200 cells/mm3." (PMID 22360788, 2012). "IVDU heroin users, but not IVDU heroin/cocaine or cocaine users, had higher plasma LPS levels despite lower plasma VL and higher CD4 counts compared to subjects with no substance abuse." (PMID 18575590, 2008). "Effect of alcohol on CD4+ cell decline appears to be independent of ART, through a direct action on CD4 cells, although alcohol and substance abuse may lead to unmeasured behaviors that promote HIV disease progression." (PMID 33889269, 2021). "Third, mental health, substance abuse, socioeconomic status, and other psychosocial characteristics, which may be important factors that impact virologic suppression and by extension CD4 response, are not measured in the HIVRN and therefore could not be examined." (PMID 28182675, 2017). "IVDU, but not non-intravenous cocaine abuse, was associated with higher plasma LPS levels, while plasma VL and CD4 counts were lower and higher, respectively, in IVDU subjects compared to those with no substance abuse." (PMID 18575590, 2008).
tuberculous meningitis (24 papers, 2008 to 2025). "CD4 T cells from the cerebrospinal fluid of humans with HIV-associated tuberculous meningitis commonly express surface OX40 protein, while CD8 T cells do not." (PMID 38110410, 2023). "Nevertheless, tuberculosis is an exception that can cause tuberculous meningitis (TBM) at any level of CD4 count as long as there is immune suppression." (PMID 40477152, 2020). "In addition, low CD4 lymphocyte counts in hospitalized patients with HIV-co-infected EPTB were found to be associated with meningeal TB and disseminated TB in a single hospital study in the USA13." (PMID 29872046, 2018). "Patients with severe TB, such as military TB and tuberculous meningitis, have been proven to have lower CD4 T-cell counts and impaired T-cell function." (PMID 38126070, 2023). "One male PLHIV with a CD4+ TL of 70 cells/mm3 had tuberculous meningitis, diagnosed after four months of LTBT, which was a probable immune reconstitution inflammatory syndrome of a previous occult TB infection." (PMID 36548687, 2022). "Patients with CM are profoundly immunosuppressed: the median CD4 count in Vietnamese patients is 16 cells/μl (which compares with a median CD4 count of 42 in Vietnamese HIV patients with tuberculous meningitis)." (PMID 25391338, 2014). "The relevant role of CD4+ cells in the pathogenesis of CNS TB is confirmed by CD4+ cell counts and TB meningitis in the HIV population." (PMID 22111973, 2011). "In another retrospective study, a total of 126 CM and 105 tuberculous meningitis patients were included; multivariate analysis showed that older age, altered mentation, lower CD4/CD8 ratios, and higher CSF cryptococcal antigen were independent risk factors for poor prognosis for CM patients." (PMID 36675447, 2023). "All four CrAg‐positive cases were TB‐index patients and were performed a CSF‐CrAg test that resulted negative in two of them (both were asymptomatic, including the participant with >100 CD4 cells/μL) and positive in two cases that had also disseminated TB and confirmed TB meningitis, respectively." (PMID 34347366, 2021). "Factors associated with three-month (early) mortality were being homeless, having low CD4+ lymphocyte count, having tuberculous meningitis, belonging to a socially disadvantaged community, having more than 35 years, and being on an antiretroviral therapy at the moment of initiating the ATT." (PMID 23316226, 2012). "Our study of human CSF T cells in HIV-associated TB meningitis helps to corroborate both the single-cell transcriptional T cell phenotypes observed in the mouse lung, as well as the expression of TNRSF4/OX40 among a sub-population of CD4 T cells at the site of infection." (PMID 38110410, 2023). "Factors associated with mortality included GCS (p = 0.032), infarcts (p = 0.004), extra-meningeal TB (p = 0.003), VPS infection (p = 0.018), low CD4 count (p = 0.009), and hyponatremia (p = 0.002)." (PMID 37964056, 2024). "Of the 22 patients who died, 63.6% (n = 14) were males, in the age group 40-49 (n = 7; 31.8%), with TB meningitis (n = 12; 54.5%), were HIV positive (n = 20; 90.9%), had CD4 cell count <100 cells/mm3 (5%), were on ART (n = 14; 63.6%), and had GCS of 9-14 (n = 13; 59.0%)." (PMID 35734322, 2022). "The 2016 WHO ART guidelines recommend that ART should be started as soon as possible and at least within 8 weeks of starting TB treatment in all TB patients infected with HIV, irrespective of CD4 count, with the possible exception of TB meningitis." (PMID 29995958, 2018).
acne (23 papers, 2013 to 2024). An inflammatory process of the sebaceous glands which is characterized by comedones, nodules, papules and/or pustules on the skin. "Intriguingly, C. acnes-specific Th17/Th1 cells are primarily found in the peripheral blood of acne patients, thus establishing these C. acnes-responding Th17/Th1 cells as a crucial CD4+ subpopulation implicated in acne pathogenesis." (PMID 37344849, 2023). "Similar to gut microbes, acne-associated and healthy-associated strains of C. acnes differentially regulate CD4+ T cell responses to induce TH17 cells that secrete either IL-17 and IFN-γ (pro-inflammatory) or IL-17 and IL-10 (anti-inflammatory) respectively." (PMID 35795664, 2022). "This early inflammatory phase is marked by macrophages and CD3(+) and CD4(+) cells, along with activated vascular adhesion molecules like E-selectin and integrin, emphasizing inflammation’s primacy role in acne development." (PMID 38791344, 2024). "has revealed prominent escalations in CD3+ and CD4+ T cells, macrophages, and IL-1α in the dermis surrounding unaltered hair follicles in individuals afflicted with acne, suggesting inflammation as a precursor to the manifestation of acne." (PMID 38550588, 2024). "Observations have been made of a substantial infiltration of CD4+ T cells in the perifollicular space of early acne lesions, further substantiating the role of T helper cells in the immune response prompted by C. acnes colonization." (PMID 37344849, 2023). "An infiltration of CD4 cells has been evidenced in the pilosebaceous follicle in the initial stages of acne; CD3, CD4, and macrophage cells were found from the beginning of formation of the microcomedone." (PMID 35889022, 2022). "The etiology and pathogenesis of acne vulgaris is briefly discussed, followed by the CD4+ T cell responses against C. acnes and their ability to form extracellular traps (ETs) in response to microbial threats." (PMID 35795664, 2022). "It is worth noting that the so-called “inflammatory components”, i.e., CD4+ T cells and macrophages, are also present in the skin and are unaffected by acne lesions." (PMID 35329904, 2022). "Because we identified cDC2 activation during the early stages of acne and because these cells have been shown to promote type 3 responses, our next approach was to create a cartography of cDC2 and IL-17+ CD4+ T cells using confocal microscopy." (PMID 34650562, 2021). "CD4+ T-cells are the major leukocytes in the early (6–72 h) inflammatory infiltrates in acne lesions, with a small portion of CD1+ dendritic cells." (PMID 25153527, 2014). "The proliferation of P. acnes will attract CD4+ lymphocytes and macrophages to microcomedone and then induce the inflammatory acne lesion with rupture of follicular wall." (PMID 24013774, 2013). "Although both CD4+ T lymphocytes and neutrophils infiltrate around acne inflammatory lesions, lymphocytes may play a more central role in early acne lesions than neutrophils, which are strongly attracted after the follicles have been disrupted." (PMID 38357543, 2024). "CD4+ T cells play a key role in the pathogenesis of acne vulgaris." (PMID 38744939, 2024). "Additionally, other inflammatory cells, especially CD4+ T cells and macrophages, are also observed in the perifollicular region and dermis in acne-uninvolved skin." (PMID 38357543, 2024). "Early acne lesions are characterized by a significant presence of CD4+ T-helper cells." (PMID 38791344, 2024). "Histological studies showed that CD4+ T cells were the most numerous cells of the white blood cell system in early-stage inflammatory infiltrations (6–72 h) in acne lesions, which suggests that they might take part in immune response triggered by the colonization of the sebaceous gland by C. acnes." (PMID 35329904, 2022).
acne (continued). "Additionally, a variety of immunologic cells including monocytes, CD4+ T-cells, and Langerhans cells, which are significantly involved in the initiation of acne inflammation, are mainly found in the deeper epidermis dermis layer as well as in the vascular layer." (PMID 32423177, 2020). "Previous studies have indicated that papules can form in under 6 h and exhibit a profound inflammatory response as evidenced by increased levels of CD4 T cells, neutrophils, and CD68+ macrophages in acne biopsies." (PMID 39143467, 2024). "Previous studies have indicated that papules can form in under 6 hours and exhibit a profound inflammatory response as evidenced by increased levels of CD4 T cells, neutrophils, and CD68+ macrophages in acne biopsies." (PMID 38854033, 2024). "A higher level of CD4 cells and macrophages in uninvolved skin of patients suffering from acne vulgaris was reported, in comparison to the skin of patients without acne." (PMID 34829964, 2021). "Interestingly, in acne and hidradenitis suppurativa, mice experiments have shown the specific contribution of C. acnes in the development of dual IL-17+IFN-γ+ CD4+ cells, although in these disorders the subsequent transdifferentiation into IL-17-IFN-γ + exTh17 cells seems less pronounced." (PMID 35967358, 2022). "In addition, non-lesional sites of acne patients exhibit lower infiltration of activated memory CD4+ T cells, plasma cells, memory B cells, M0 macrophages, neutrophils, resting mast cells but higher infiltration of Tregs and resting dendritic cells relative to skin of healthy individuals." (PMID 33760854, 2021). "The fact that CD69+ absolute cell number increased (for both CD4+ and CD8+ T cells) at the CC stage and plateaued at the PA stage (a non-significant slight decrease was measured) suggests that these TRM cells might be involved and proliferate in the very early steps of acne pathogenesis." (PMID 34650562, 2021). "The count of CD4+ cells and CD83+ mature dendritic cells was significantly higher both in the papillary dermis and around follicles in acne lesions, when compared with non-lesional skin." (PMID 25153527, 2014).
acute respiratory distress syndrome (23 papers, 2015 to 2024). Progressive and life-threatening pulmonary distress in the absence of an underlying pulmonary condition, usually following major trauma or surgery. "Indeed, higher CD8:CD4 T cell ratios were previously associated with acute respiratory distress syndrome following respiratory viral infection, most likely due to damage caused by CD8+ cytotoxic T cells." (PMID 39769461, 2024). "Though our patient viral load and CD4+ T‐cell count was unknown, it has been shown that HIV patient with low CD4+ T‐cell count, and high viral load have a high risk of acute respiratory distress syndrome." (PMID 35846931, 2022). "TIM-1+ B cells were also determined to promote Foxp3 expression in CD4+ T cells in acute respiratory distress syndrome." (PMID 30917149, 2019). "Recent studies have revealed that lung inflammation mediated by CD4+ T cells may contribute to the pathogenesis of acute respiratory distress syndrome (ARDS)." (PMID 25887535, 2015). "Neutrophilia was present in patients who progressed to acute respiratory distress syndrome (ARDS), and total lymphocyte count, and CD4+ T cells decreased in severe or critical patients." (PMID 35386702, 2022). "A comparison of P2rx7fl/fl mouse with CD4+ T (with CD4-cre)-, myeloid cells (with LySM-Cre)- or airway epithelial cell (with CCT-cre)-specific P2rx7 KO mice revealed a role for CD4+ T cell and myeloid cell P2X7 in the development of acute respiratory distress syndrome." (PMID 37175933, 2023). "It is suspected that the acute respiratory distress syndrome (ARDS)-like picture in SARS-CoV-2-infected patients is precipitated and worsened by the excess monocytes in response to GM-CSF, which is released by rapidly activated CD4+T-cell lineage." (PMID 32499983, 2020).
injury (23 papers, 2010 to 2024). Damage inflicted on the body as the direct or indirect result of an external force, with or without disruption of structural continuity. "A lymphocyte-mediated mechanism with an altered CD4/CD8 ratio has been implicated in the pathogenesis of alcohol-related liver injury, and an altered CD4/CD8 ratio has been observed in people with schizophrenia spectrum disorders." (PMID 37859501, 2023). "Increased numbers of Interleukin-17-producing CD4+ T cells (Th17) have been found in association with hepatitis B virus (HBV)-induced liver injury." (PMID 21639870, 2011). "Since CD4+CD25+Foxp3+ Tregs play crucial roles in the TGF-β mediated regulation of immune response in acute lung injury, we next analyzed the levels of CD4+CD25+Foxp3+ Tregs in the peripheral blood from sham, LPS-instilled, and LPS-instilled QD-treated mice." (PMID 37292149, 2023). "In Con A-induced liver injury, lymphocyte (especially CD4+ T cell) activation and infiltration play a central role in inducing liver damage." (PMID 34503553, 2021). "In conclusion, this study demonstrated the efficacy of HLSCs in the prevention of the ConA-induced acute liver injury through the modulation of MDSCs and CD4+ T cell migration and cytokine secretion." (PMID 30635035, 2019). "On the other hand, CD4+ T cells have been confirmed to increase the ConA-induced acute liver injury." (PMID 30635035, 2019). "Perinatal HI brain injury induced significant infiltration of CD4+ T cells into the injured cerebral hemisphere, and this was significantly reduced by all hUCB cell types tested." (PMID 29454374, 2018). "We therefore tested how MHC-II expression in Schwann cells affected the local presence of CD4+ T helper cells after traumatic nerve injury." (PMID 28970572, 2017). "When patients with primary MHTN related kidney injury have decreased CD4+CD25+ cells, their lymphocytes would react significantly more strongly to antigens, leading to higher levels of cytokine (IL-2, IL-4, and IL-6) production." (PMID 27278520, 2016). "Besides macrophages, CD4+CD25+Foxp3+ Tregs (regulatory T cells) play a critical role in resolving acute lung injury." (PMID 37292149, 2023). "The trauma patients had lower IFN-γ production by CD4+ Th1 cells compared to the control group." (PMID 36697474, 2023). "Furthermore, Tregs purified from BeO-exposed mice suppressed the proliferation of anti-CD3–stimulated CD4+ T cells in vitro in a similar manner to that observed in LPS-induced lung injury." (PMID 35819849, 2022). "We observed that CD4+T/CD8+T in peripheral blood T cells of craniocerebral trauma rats were significantly higher than those of normal rats, and the ratio of CD4+CD25+Foxp3 (Foxp3)+Regulatory T cell (Treg) was significantly lower than that of normal rats and caused increased secondary inflammation." (PMID 35874774, 2022). "Furthermore, CD4 T cells were shown to be critical for the pro-inflammatory immune response in a model of ischemia and reperfusion-induced liver injury." (PMID 31143178, 2019). "Although we cannot rule out that macrophage β-catenin activation may regulate Treg production through other pathways, our findings add a non-negligible mechanism for the crosstalk between macrophages and CD4+ T cells, providing insights into the pathophysiology of acute liver injury." (PMID 39560996, 2024). "Here, we investigated the association between the number change of CD4+CD25+ cells and the development of MHTN related kidney injury using a case-control study to test the hypothesis that a numerical or functional deficit of CD4+CD25+ cells might trigger the development of disease." (PMID 27278520, 2016). "In summary, CD4+ T cells, CD8+ T cells, and Tregs, the major coordinators of immunopathological lesions, play essential roles in the pathogenesis of HSK and corneal injury." (PMID 35126129, 2021). "The expression of CD69 and CD25 increased both in CD4+ and CD8+ populations reaching maximum levels three months after HI brain injury." (PMID 22567156, 2012).
injury (continued). "In this non-interventional prospective study, the immune response of CD4+ Tregs and Th17 cells in a post-traumatic setting in humans with and without severe traumatic brain injury was investigated." (PMID 36142962, 2022).
kidney (23 papers, 2011 to 2025). "The levels of preadipocytes, CD8+ effector memory T (Tem), CD4+ T, and CD4+ Tem cells in the TME differed significantly between the two age groups in urogenital cancers." (PMID 33436826, 2021).
lymphoproliferative disorder (23 papers, 2005 to 2026). "Transfer of donor CD4+CD25+ Tregs into neonatal Foxp3-deficient mice rescued the lymphoproliferative disorder in recipient mice, suggesting that Foxp3 is a critical regulator of CD4+CD25+ Treg function." (PMID 35371055, 2022). "The lethal lymphoproliferative syndrome in SF mice is predominantly caused by CD4+ T cell-induced pathology." (PMID 29270168, 2017). "A repeat skin biopsy revealed an EBV-positive lymphoproliferative disorder consistent with grade 3 lymphomatoid granulomatosis, with predominance of CD4+ T cells." (PMID 42112412, 2026). "Some PCMZL/LPD show overlapping clinical and histopathologic features with primary cutaneous CD4‐positive small or medium lymphoproliferative disorder." (PMID 40495407, 2025). "The clinical preparation of virus-specific T cells for the control of post-transplant lymphoproliferative disorders was shown to require the presence of CD4+ T cells." (PMID 29599759, 2018). "This lethal lymphoproliferative syndrome is predominately mediated by CD4+ T cells in humans and mice." (PMID 29270168, 2017). "It is suggested that CD4+ T cell count may be insufficient to predict the risk of HIV-related disease, especially lymphoproliferative disorders." (PMID 37744454, 2023). "An elevated/abnormal CD4/CD8 T-cell ratio indicates an atypical lymphocytic infiltrate and may suggest a lymphoproliferative disorder." (PMID 40103683, 2025). "We did not detect an increase in blasting cells or in the expression of activation markers between ABM and C2ABM CD4+ T cells, ruling out a lymphoproliferative disorder (data not shown)." (PMID 22101858, 2012). "In summary, a CD4 stain may be helpful to support or rule out a lymphoproliferative disorder." (PMID 40103683, 2025). "Between 1996 and 2002, out of 837 lymph node FNAs submitted for flow cytometry analysis, 85 cases showed an elevated CD4/CD8 ratio, defined as greater than or equal to 4, without definitive evidence of a lymphoproliferative disorder." (PMID 16153296, 2005). "An elevated CD4/CD8 ratio on FCM is a nonspecific finding which may be seen in both reactive and lymphoproliferative disorders." (PMID 16153296, 2005).